MIF (macrophage migration inhibitory factor)
Diseases named in the same sentence as MIF in open-access papers (continued):
Sharing a sentence is not in itself a finding about the gene and the disease.
breast cancer (continued). "This study provides evidence that the WISP1/Src/MIF axis plays a pivotal role in driving the aggressiveness of non-invasive MCF7 breast cancer cells, a widely used cellular model for ER+ breast cancer studies, particularly through regulation of cell survival, migration, and ECM remodeling." (PMID 41597235, 2026). "Importantly, using KM-plotter survival analysis, we found that higher expression of MIF significantly correlates with worse overall survival in TNBC subjects exclusively, compared to other hormonal breast cancer subtypes." (PMID 32943608, 2020). "MIF was first reported to promote MDSC functional accumulation as a consequence of breast cancer cell secretion and paracrine activity towards M-MDSC differentiation in mouse models of breast cancer." (PMID 33324425, 2020). "Finally, we detected an aberrant protein expression of MIF in various human and murine TNBC cell lines compared to cells from other breast cancer subtypes." (PMID 32943608, 2020). "The UALCAN analysis showed that only CXCL12 had a lower expression level in basal-like (triple-negative) breast cancer compared with luminal-like breast cancer, while CXCL5, IDO1, MIF, PTGS2, and VEGFA all had increased expression levels in basal-like breast cancer." (PMID 31293831, 2019). "In addition, the Kaplan–Meier survival analysis showed that increased MIF and VEGFA expression levels in breast cancer patients correlated with a reduced survival rate." (PMID 31293831, 2019). "It was reported that MIF and CD74 are upregulated in subjects with breast cancer (BC)." (PMID 28477623, 2017). "In this study, we first knocked down the MIF using small interfering RNA (siRNA) and built the stable low expression MIF breast cancer cells (siRNA-MIF-MCF-7) and the negative control cells (siRNA-NC-MCF-7)." (PMID 26911617, 2016). "Expression of MIF often correlates with the state of hypoxia, although MIF expression is not dependent on hypoxia or HIF1α in MCF-7 breast cancer cells." (PMID 26352431, 2015). "In our study, the human adipokine chip test of the co-culture supernatant of MCF-7 cells and adipocytes revealed some altered proteins which are reported to be involved in the regulation of proliferation and metastasis of breast cancer cells, such as IGFBP-2, IL-6sR, IL-8, leptin, MIF, and TGF-β." (PMID 25747684, 2015). "Level of co-expression of MIF and CD74 could be a surrogate marker for efficacy of anti-angiogenic drugs, particularly in TRN breast cancer tumors." (PMID 24939415, 2014). "Level of co-expression of MIF and CD74 could be a surrogate marker for efficacy of anti-angiogenic drugs, particularly in TRN breast cancer tumor." (PMID 24939415, 2014). "In own prior work leading up to the current investigation, we observed strong MIF expression in MCF-7 and ZR-75-1 breast cancer cells, and blockade of MIF secreted from these cells suggested a causal role of extracellular MIF in breast cancer cell survival involving the AKT/PI3K pathway." (PMID 19602265, 2009). "MIF was abundantly expressed in the non-invasive breast cancer cell lines MDA-MB-468 and ZR-75-1, but not in invasive MDA-MB-231 cells, which in turn expressed higher levels of the MIF-receptor CD74." (PMID 19602265, 2009). "Additionally, 1-(9′-methyl-3′-carbazole)-3, 4-dihydro-β-carboline (MCDC), another synthetic compound, demonstrated inhibitory effects on macrophage migration inhibitory factor (MIF), AKT phosphorylation, and the expression of S phase-related proteins in breast cancer cells." (PMID 39863145, 2025). "Since MIF has been shown to have a tumor-immunomodulatory role by inducing myeloid derived suppressor cell (MDSC) accumulation within the tumor, it is likely that the inhibition of autophagy will also induce immunomodulation in breast cancer tumors, but these effects remain to be tested." (PMID 31963754, 2020).
breast cancer (continued). "It is not known whether CXCL12 and MIF are increased in lungs of irradiated breast cancer patients but future research could investigate the sputum, serum or urine of breast cancer patients in the acute or long-term response to radiation." (PMID 26396176, 2015). "Experimental data published show that MIF suppression in breast cancer cell lines does not affect their proliferation in vitro but causes delayed tumor growth in mice, increasing the prevalence of an immune suppressive myeloid-derived population within the tumor." (PMID 24939415, 2014). "Thus, the increased serum level of MIF in BCP could be a non-specific signature of a systemic response to breast cancer with immune and metabolic implications." (PMID 24939415, 2014). "Despite these differences that may in part be due to the different cohorts studied, the link between MIF levels and ER/PR status as observed in our cohort is of interest, because these parameters may be molecularly connected to MIF through JAB1/CSN5, which is abundantly expressed in breast cancer." (PMID 19602265, 2009). "Experiments were conducted using a single ER+ breast cancer cell line (MCF7), and in vivo validation of the WISP1/Src/MIF axis is lacking." (PMID 41597235, 2026). "It has been previously shown that MIF mediates CD74 induction for the regulation of the PI3K/AKT signaling, but the mechanism is not known in TNBC and breast cancer cells." (PMID 39056676, 2024). "To date, co-expression of MIF and CD74 has not been studied in breast cancer but it has been described in prostate and non-small cell lung cancer." (PMID 24939415, 2014).
autoimmune disease (98 papers, 2007 to 2025). A disorder resulting from loss of function or tissue destruction of an organ or multiple organs, arising from humoral or cellular immune responses of the individual to their own tissue constituents. "This dual role is particularly evident in chronic inflammatory and autoimmune diseases, where MIF is implicated in sustaining inflammation, resulting in persistent tissue injury and dysfunction." (PMID 41159021, 2025). "MIF is implicated in a wide range of autoimmune diseases, reflecting its diverse role in immune regulation." (PMID 41159021, 2025). "Beyond its enzymatic activity, MIF is known as a versatile cytokine implicated in inflammation and associated conditions such as obesity, diabetes mellitus, autoimmune diseases, and cancer." (PMID 39517120, 2025). "Accordingly, inhibition of MIF has been proposed as a potentially effective therapeutic strategy for the treatment of inflammatory and autoimmune diseases, in particular in conditions associated with glucocorticoid resistance or glucocorticoid dependence." (PMID 40092999, 2025). "Ibudilast has shown efficacy in multiple sclerosis, an autoimmune disease in which a high-expression MIF genotype confers risk for progressive disease." (PMID 38838773, 2024). "An array of inflammatory and autoimmune diseases has been linked to the dysregulated activity of MIF." (PMID 38915940, 2024). "Peak 56 (m/z 12.345) was associated with macrophage migration inhibitory factor (MIF), which is a pro-inflammatory cytokine involved in many chronic inflammatory and autoimmune diseases, which promotes tumor growth, metastasis and neo-angiogenesis." (PMID 37958700, 2023). "Although high expression of MIF is associated with the pathogenesis of several autoimmune diseases, MIF is also a highly conserved cytokine constitutively expressed in a variety of mammalian tissues under normal physiological conditions." (PMID 37616250, 2023). "In some autoimmune diseases, MIF is a susceptibility factor, while in others MIF is involved mainly in disease progression." (PMID 34662363, 2021). "Macrophage migration inhibitory factor (MIF) is a multifunctional cytokine that controls proinflammatory response and is linked with numerous inflammatory and autoimmune diseases." (PMID 33923488, 2021). "Recently, many studies have indicated that MIF-173G/C is associated with the pathogenesis and progression of autoimmune diseases." (PMID 32410863, 2020). "Accordingly, higher MIF serum levels have been shown to be associated with the severity of various inflammatory and autoimmune diseases." (PMID 31370326, 2019). "MIF acts as an inflammatory cytokine, and it has been implicated in inflammatory and autoimmune diseases." (PMID 30976114, 2019). "Two polymorphisms in the promoter region of the MIF gene, rs755622 and rs5844572, have been found to be associated with the severity of inflammatory and autoimmune diseases including autoimmune hepatitis." (PMID 31370326, 2019). "Macrophage migration inhibitory factor (MIF) is a pleiotropic, pro-inflammatory cytokine that has been implicated in the pathogenesis of several inflammatory disorders, autoimmune diseases, and tumors." (PMID 30348174, 2018). "Macrophage migration inhibitory factor is a key mediator of inflammatory responses and innate immunity and has been implicated in the pathogenesis of several inflammatory and autoimmune diseases." (PMID 30083544, 2018). "In line with this, MIF has been implicated in the progression of many inflammatory and autoimmune diseases such as rheumatoid arthritis, asthma, sepsis, inflammatory bowel disease, systemic lupus erythematosus, and cancer." (PMID 29095944, 2017). "The pleiotropic roles of MIF and MIF alleles on the immunopathogenesis of infectious and autoimmune diseases have been documented." (PMID 27014277, 2016).
autoimmune disease (continued). "In another autoimmune disease, systemic sclerosis, the MIF-173 polymorphism was associated with the development of the diffuse and more severe form of the disease in a large meta-analysis." (PMID 27014277, 2016). "The role of MIF in immune and inflammatory states, including a range of human autoimmune diseases, is now well established, as are the relationships between MIF polymorphisms and a number of inflammatory diseases." (PMID 26617609, 2015). "MIF has been implicated in the pathogenesis of multiple systemic and organ-specific autoimmune diseases because it promotes the activation and secretion of proinflammatory cytokines by immune cells." (PMID 24667663, 2014). "A similar example for dual effect of MIF polymorphism is observed in another autoimmune disease, systemic lupus erythematosus." (PMID 24667663, 2014). "In fact, the correlation between increased MIF level, MIF gene polymorphism and steroid resistance has been reported in several autoimmune diseases and in human CEM T-cell lines." (PMID 22551315, 2012). "In view of previously published work suggesting a role for MIF in the expression level of TLR4, these results suggest an association between TLR4 and MIF in patients with autoimmune disease." (PMID 20596538, 2010). "The role of MIF in the development of ICM caused by autoimmune diseases has yet to be established." (PMID 40092999, 2025). "However, as will be discussed in the next section, MIF is also involved in the pathogenesis of disease, influences disease severity, and is associated with several inflammatory and autoimmune diseases." (PMID 40092999, 2025). "Additionally, recent studies also indicate that the upregulation of MIF in autoimmune diseases is associated with the severity of the disease, and the use of MIF monoclonal antibodies can inhibit the inflammatory response." (PMID 39614150, 2024). "MIF is a multipotent cytokine which is associated with inflammatory and autoimmune diseases." (PMID 37946732, 2023). "The MIF gene has polymorphisms of transcription factors and the promoter region, and these can significantly affect the transcription of MIF gene, which determines its ability to modulate susceptibility and severity of infectious and autoimmune diseases." (PMID 36824264, 2023). "Genetic studies have identified associations between MIF polymorphisms and autoimmune diseases." (PMID 35563556, 2022). "MIF is a proinflammatory cytokine encoded within a functionally polymorphic genetic locus, the pro-inflammatory nature of which is often associated with the spread of inflammation and autoimmune diseases." (PMID 36714563, 2022). "MIF acts as a pleiotropic inflammatory cytokine that is important in both innate and adaptive immunological responses and has been implicated in the pathogenesis of autoimmune diseases, including RA and systemic lupus erythematosus (SLE)." (PMID 34535196, 2021). "MIF is implicated in the pathogenesis of several immunoinflammatory and autoimmune diseases." (PMID 30983881, 2019). "MIF plays a dual role in autoimmune diseases; for example, alleles that promote gene expression protect against systemic lupus erythematosus (SLE) but, in patients with established disease, alleles that reduce expression protect against disease complications and multiple organ involvement." (PMID 27014277, 2016). "Given that current therapeutic investigations revealed that MIF and IL-17 deficiency through genetic deletion or Abs neutralization results in protection or release from several animal models of inflammatory and autoimmune disease, clinical application still needs further in-depth research." (PMID 25861163, 2015). "Based on findings published to date, it can be postulated that MIF promoter polymorphisms and consequent changes in MIF expression contribute to the susceptibility and clinical severity of many inflammatory and autoimmune disorders where MIF has been implicated." (PMID 26617609, 2015).
autoimmune disease (continued). "As a multifunctional proinflammatory cytokine, MIF is demonstrated to participate in innate and adaptive immune responses and is known to be implicated in the pathogenesis of many autoimmune diseases, such as inflammatory bowel disease (IBD), rheumatoid arthritis, and vitiligo vulgaris." (PMID 25861163, 2015). "Therefore, it could be considered that MIF-173G/C polymorphism could increase the susceptibility of autoimmune diseases, while there may be the discrepancy of disease entity." (PMID 32410863, 2020). "Thus we speculate that MIF may be implicated in inflammatory and autoimmune disease through interacting with Th17 cells." (PMID 25861163, 2015). "Studies suggest that ART modulates the balance of Th17/Treg cells in autoimmune disease models and inhibits macrophage migration by targeting macrophage migration inhibitory factor (MIF)." (PMID 40934008, 2025). "In accordance with the main role of inflammation in MS, recent studies showed that the macrophage migration inhibitory factor (MIF) represents a key factor in several autoimmune diseases, including MS, where it is found to be overregulated." (PMID 40722922, 2025). "MIF plays a critical role in mediating resistance to pathogens and promoting several types of immune and autoimmune diseases." (PMID 40092999, 2025). "The role of MIF in inflammation, immune responses, and various disease pathologies such as autoimmune disorders and cancer has been increasingly recognized, yet several key areas remain underexplored." (PMID 40092999, 2025). "For instance, in autoimmune diseases such as SLE and RA, MIF levels correlate with disease severity, and in cancers, including colorectal cancer, high MIF levels are linked to poor patient outcomes." (PMID 40092999, 2025). "MIF is a potent inducer of inflammatory responses participating in innate immunity and various autoimmune diseases." (PMID 39200138, 2024). "Macrophage migration inhibitory factor (MIF) is a multifunctional protein crucial in inflammatory and autoimmune diseases." (PMID 39416784, 2024). "Studies have reported a positive correlation between MIF and Th17 cells in autoimmune diseases, and IL-17A expression is impaired in MIF knockout mice." (PMID 39614150, 2024). "MIF also significantly impacts autoimmune diseases such as systemic lupus erythematosus (SLE) and inflammatory bowel disease (IBD) by exacerbating inflammation." (PMID 39337534, 2024). "MIF appears to be a candidate as a new biomarker and target of novel therapeutics against numerous neurologic diseases ranging from cancer, autoimmune diseases, vascular diseases, neurodegenerative pathology to psychiatric disorders." (PMID 38178143, 2024). "The membrane protein CD74 is the high-affinity receptor of MIF, and MIF can regulate the activity of CD74, causing homeostatic disorders such as inflammation, tumor and autoimmune diseases." (PMID 38625586, 2024). "Aside from its role in infectious diseases, MIF plays a role in inflammatory diseases such as asthma or atherosclerosis, various forms of cancer, several autoimmune diseases, burn injuries, wound healing, and even free-flap ischemia." (PMID 38275363, 2023). "MIF is known to be involved in the progression of inflammatory and autoimmune diseases and interacts with various receptors, including CXCR2, CXCR4, and CD74 (Bucala 2013, Morrison and Kleemann 2015)." (PMID 37740953, 2023). "In chronic inflammation and autoimmune diseases, MIF is thought to play a role in maintaining inflammation, leading to persistent tissue damage and dysfunction." (PMID 38275363, 2023). "Circulating concentrations of MIF are elevated in infected patients, inflammatory conditions, and autoimmune diseases." (PMID 38035087, 2023). "The findings will provide a novel clue for the therapy of MIF-induced pathogenesis of neurodegenerative diseases (AD), autoimmune disorders (MS), CNS tumor, as well as other inflammatory neuropathology." (PMID 35624475, 2022).